LAG3 (lymphocyte activating 3)
Diseases named in the same sentence as LAG3 in open-access papers (continued):
Sharing a sentence is not in itself a finding about the gene and the disease.
tumor (continued). "Fibrinogen-like protein 1 (FGL-1) is a major LAG-3 functional ligand independent from MHC-II and induces a significantly reduced anti-tumor response." (PMID 39057061, 2024). "The transcriptomic profile that we found in tumour-reactive CD137+ CD8+ T cells suggested an exhausted/activated-like phenotype with increased expression of TNFRSF9, LAG3, PDCD1, TIGIT and HLA-DPA1/HLA-DQA1." (PMID 38986249, 2024). "Significantly, LAG3 and PD1 blockade had achieved a pronounced reduction (p < 0.05) in tumor’s weight and growth in TNBC BALB/c mice compared with a single blockade of LAG3 or PD-1 which showed less reduction in tumor weight." (PMID 38397971, 2024). "Tregs, as one of the most important parts of immunosuppressive cells, can inhibit tumor-specific immune responses with the co-inhibitory molecules such as CTLA-4, TIGIT, LAG3, and CD28, and promote immune evasion, thus facilitating tumor cell proliferation." (PMID 38671348, 2024). "In consideration of M2 macrophages and Treg cells exhaust CD8+T cells in tumor immune microenvironment (TIME), we explored the correlation between several immune checkpoints expression (PD-1, TIM-3, CTLA-4, LAG3 and TIGIT) and TIBs in the TCGA database." (PMID 38762825, 2024). "CTLA-4, LAG3, TIM-3, and PD-1 are the primary co-inhibitory checkpoints involved in tumor development and progression in CRC." (PMID 39839672, 2024). "Further analysis of individual spots revealed a significant positive correlation between tumor infiltration by NK cells (CD56+) and average BAP1, NF2, MTAP, and LAG3 expression levels in MPM (ρ > 0.4)." (PMID 38994676, 2024). "Ieramlimab (LAG525) is a humanized IgG4 monoclonal antibody developed by Novartis that inhibits the interaction between LAG3 and MHC-II, as well as FGL-1, thereby suppressing tumor cell growth." (PMID 39743998, 2024). "Remarkably, the decrease in expression of PD-1, LAG-3, and TIM-3 in ITK-KO CD19-CAR-T cells, compared with nt-KO CD19-CAR-T cells, remained significant after multiple rounds of exposure to the targeted tumor cells." (PMID 39589809, 2024). "Recent studies have identified that LAG-3, along with PD-1 and CTLA-4, is a common receptor of nodal immune checkpoint, participating in tumor immune response and tumor immune escape." (PMID 39252941, 2024). "Remarkably, there is a significant expression of lymphocyte activation gene-3 (LAG-3) and programmed cell death protein-1 (PD-1) in the lymphocytes that infiltrate the tumor." (PMID 38397971, 2024). "LAG3+ T cells highly expressed LAG3 and CTLA4+ T cells highly expressed CTLA4 and TIGIT, which were also higher in tumor tissues than in normal tissues." (PMID 38604154, 2024). "Tumor-infiltrating hepatic CD8+ T and NK cells upregulated the expression of lymphocyte activation gene-3 (LAG-3) and exhibited stronger antitumor activities after anti-FGL1 treatment." (PMID 38973608, 2024). "Treatment with anti-LAG-3 monoclonal antibodies enhances both the number and effector function of tumor-specific CD8+ T cells in TRAMP mice, thereby slowing tumor growth." (PMID 39120585, 2024). "anti-LAG-3 ICT was the most potent approach, with the most effective control of tumor growth and 66% survival rate at 60 days post-inoculation (study endpoint)." (PMID 38349406, 2024). "Tumor-promoting genes such as CD163 and CD209 were highly expressed in the myeloid cells, and depletion marker genes such as TIGIT, LAG3 were highly expressed in NK/T cells." (PMID 38582791, 2024). "The results demonstrated a positive correlation between FANCD2 and immune checkpoints in most tumor tissues, including CTLA4, HAVCR2, LAG3, PDCD1, PDCD1LG2, SIGLEC15, TIGIT, and particularly CD274." (PMID 38443946, 2024). "We found that HER2 CAR‐T cells acquired enhanced activation after encountering tumor antigens, as indicated by the greater upregulation of TIM‐3 and LAG‐3, along with a superior expansion potential compared to SIA‐CIgG CAR‐T cells." (PMID 39178136, 2024).
tumor (continued). "LAG-3 has also been observed to bind to TCR in both CD8+ and CD4+ T-cells leading to the inhibition of TCR-dependent tumor cascades and the curbing of T-cell responses." (PMID 39343796, 2024). "In vivo results showed that ZGGS15 had better anti-tumor inhibition than single anti-LAG-3 or anti-TIGIT agents and demonstrated a synergistic effect when combined with nivolumab, with a significantly higher tumor growth inhibition of 95.80% (p = 0.001)." (PMID 38724599, 2024). "LAG-3 represents another promising treatment target after PD-L1 and CTLA-4; it induces T cell depletion and blocks T cell proliferation, preventing anti-tumor responses." (PMID 39397869, 2024). "Meanwhile, studies have found that LAG-3 and PD-1 were widely co-expressed on CD4+ and CD8 + T cells, especially on tumor-infiltrating T cells." (PMID 38177102, 2024). "Elevated LAG-3 and PD-1 levels significantly inhibit CD8+ T-cell function, rendering them unable to kill tumor cells." (PMID 39057061, 2024). "Here, we report the findings of a preclinical study of ZGGS15, a novel bispecific monoclonal antibody (BsAb) that can simultaneously inhibit LAG-3 and TIGIT alone or in combination with an anti-PD-1 antibody, exhibiting exceptional anti-tumor efficacy." (PMID 38724599, 2024). "LAG-3 was overexpressed on TIL in HNSC patients, and its expression correlated with high pathological grade, tumor size, and poorer prognosis." (PMID 39052123, 2024). "We also compared the differences in expression levels of TEX marker genes (HAVCR2, TIGIT, CTLA4, LAG3, and PD1) and the putative tumor stem cell marker genes (CD44 and PROM1) between high and low TEXSRGs-score groups in clinical tumor samples using qRT-PCR." (PMID 37957420, 2023). "In tumour models, Egr2high CD8 + TILs expressed high levels of PD-1, Tim3 and Lag3, but maintained their proliferative ability and functionality." (PMID 36342511, 2023). "Immune checkpoint molecules like CTLA4, PD1, PDL–1, LAG3, and TIM–3 inhibit the immune response in different tumor types at different phases of tumor development." (PMID 37056346, 2023). "Gene expression analysis in dMMR/MSI-H CRC demonstrated high levels of the immune checkpoints CTLA-4, PD-1, PD-L1, LAG-3, and IDO in different compartments, such as tumor-infiltrating lymphocytes, tumor stroma, and the invasive front of the tumor." (PMID 37894457, 2023). "Immune checkpoints are a large group of molecules expressed in immune cells, antigen-presenting cells, tumor cells, etc. and play a role in inhibiting or activating the acquired immune system, including PD-1, PD-L1, CTLA-4, LAG3, B7-H3, TIM3, etc.." (PMID 37002211, 2023). "Since LAG3, PDCD1 and TIGIT have long been identified as key immune checkpoints in ccRCC, their blockade has demonstrated satisfactory anti-tumor efficacy in preclinical and clinical studies." (PMID 37679715, 2023). "The expression profile of inhibitory coreceptors on tumor-infiltrating T cells from patients with NSCLC shows a clear correlation between PD-1, Tim-3, CTLA-4, LAG-3, and BTLA expression on intratumoral CD8( +) T cells." (PMID 37567938, 2023). "Our recent high-dimensional mass cytometry analyis showed that PD-L1 blockade in MC38 tumor-bearing mice selectively induces expansion of tumor-infiltrating T cells that co-express activating (ICOS) and inhibitory (LAG-3, PD-1) molecules." (PMID 36997666, 2023). "The interaction occurs by binding D1 and D2 domains of LAG-3 with FGL-1, leading to reduced IL-2 levels in the tumor microenvironment." (PMID 36680187, 2023). "Results obtained from single and multiplex immunohistochemical staining revealed significantly lower levels of immune cell infiltration and expression of PD1, TIM3, TIGIT, LAG3, and CTLA4 in liver metastases compared to the primary tumor." (PMID 37828574, 2023). "High beta-2 microglobulin (B2M), LAG-3, CD25, and 4-1BB in tumor; high B2M, CD45, CD4 in stroma, and low fibronectin in the macrophage compartment, correlated with prolonged PFS." (PMID 37057033, 2023).
tumor (continued). "Based on TCGA HNSCC tumor bulk dataset, patients with HNSCC had higher TIGIT, LAG3, and CD276 expression levels than healthy individuals." (PMID 38096229, 2023). "CD69+CD8+ TM cells had higher levels of Ki67, CD223 (LAG3), and CD279 (PD-1) than did CD69−CD8+ TM cells, suggesting these CD69+CD8+ TM cells were highly proliferating tumor-reactive T cells." (PMID 36759517, 2023). "The infiltration of CD4 and CD8 T cells, as well as the levels of the TEX marker genes (HAVCR2, TIGIT, CTLA4, LAG3, and PD1) and tumor stem cell marker genes (CD44 and PROM1), were all greater in tissue samples with high TEXSRGs-score." (PMID 37957420, 2023). "TCF‐1+ TILs significantly correlated with pathological stage, tumor grade, CD8+ TILs density, and PD‐1, LAG‐3, and TIM‐3 expression levels in TILs." (PMID 37536668, 2023). "LAG3 and FGL1 expression promote tumor development by suppressing the immune system and are amongst the most promising immune checkpoints." (PMID 36810079, 2023). "Another LAG-3-PD-1 BsAb, RO7247669, targets and binds PD-1/LAG-3+ T cells and leads to CTL-induced immune responses against tumor cells." (PMID 37670328, 2023). "Targeting the elevated expression of LAG-3 on CD8+ and CD4+ T cells in the blood and bone marrow of patients with multiple myeloma will help enhance the proliferative and anti-tumor capacity of T cells." (PMID 37055849, 2023). "LAG-3 is a type I transmembrane protein with four Ig-like domains expressed on exhausted CD4 and CD8 tumor-infiltrating T-cells and T-regs in peripheral blood and tissue, contributing to immunoescape mechanisms." (PMID 38067208, 2023). "We further analyzed the tumor microenvironment between different RiskScore groups, and it was also apparent that the expression of PDCD1, CD274, CTLA-4, HAVCR2 and LAG3 in the low-RiskScore group was relatively high." (PMID 37154982, 2023). "In clinical immunotherapy, a LAG-3 Ig fusion protein named IMP321 was first used in advanced renal cell carcinoma patients and resulted in reduced tumor growth and improved progression-free survival." (PMID 36960057, 2023). "OAC patient-derived PBMCs co-cultured with OE33 OAC cells upregulated LAG-3 and downregulated the co-stimulatory marker CD27 on T cells, highlighting the direct immunosuppressive effects of tumour cells on T cells." (PMID 36445478, 2023). "We believe that LAG-3 and CD8 expression levels in the tumor microenvironment have potential value as predictive biomarkers of ICB responses in patients with advanced HCC prior to ICB treatment." (PMID 37342338, 2023). "We used a well-annotated cohort of PDAC patients, for whom we had long-term survival data, and analyzed the expression levels of TIM3, IDO, B7H4, LAG3, VISTA and PD-L1 in cancer cells by IHC to obtain an overview of IC expression in this neoplasia." (PMID 36768480, 2023). "To investigate the immune profiles of c-Scorehi tumors across the 25 TCGA tumor types, we evaluated immunomodulatory genes involved in immune checkpoint blockade response, (CD274 [PD-L1], PDCD1 [PD-1], HAVCR2 [TIM3], LAG3, TIGIT, CTLA4, and FASLG)." (PMID 37558751, 2023). "REP TILs encompassed a greater abundance of CD4+ than CD8+ T cells, with increased LAG-3 and low PD-1 expressions in both CD4+ and CD8+ T cell compartments compared with the pre-REP TIL and tumor T cells." (PMID 37484198, 2023). "Expression levels of B7-H3, PD-L1, Tim-3, LAG3, VISTA, and STING as well as of CD40 and CD80 were significantly elevated in tumor boundary CD11c+ segments." (PMID 38044986, 2023). "Over time, Cxcr3 and Klrg1 were progressively decreased on tumor-specific T cells infiltrating PDA and these Cxcr3-Klrg1- T cells co-expressed PD-1 and Lag-3, markers that identify TEX cells defective in IFNγ production." (PMID 36472588, 2023).
tumor (continued). "Moreover, Durante et al32 analyzed 8 primary UMs and 3 metastases with single-cell RNA sequencing (scRNAseq) and showed that CD8+ T cells within the tumor express the immune checkpoint lymphocyte-activation gene 3 (LAG3), which may contribute to creating an immunosuppressive environment." (PMID 37193315, 2023). "In cancer, a sort of chronic inflammation with the presentation of tumor antigens persists, and multiple inhibitory receptors, such as CTLA-4, PD-1, PD-L1, LAG-3 and Tim-3, are permanently expressed, especially in MSI-H CRCs with a high immunoscore." (PMID 37511431, 2023). "One of the typical hallmarks of the tumor microenvironment is the up-regulation of inhibitory receptors including CTLA-4, TIM-3, PD1, LAG-3, and TIGIT on the surface of cytotoxic lymphocytes." (PMID 37629138, 2023). "In the field of tumor immunotherapy research, the six immune checkpoints PDCD1, CD274, CTLA-4, LAG-3, TIGIT, and HAVCR2 can inhibit the proliferation, activation and effector functions of T cells, and maintain the immune homeostasis in the body." (PMID 37810780, 2023). "These molecules, such as PD-L1, LAG-3, CTLA-4, and CD272, promote the reduction in the immune response and tumor tolerance." (PMID 37766309, 2023). "Further comparison of immune infiltration, tumor mutation load, and immunophenoscore (IPS) comparison between the 2 groups indicates that the high-risk group could potentially demonstrate a heightened sensitivity towards immunotherapy checkpoints PD-1, CTLA-4, IL-6, and LAG3 in ccRCC patients." (PMID 37653791, 2023). "Increased expression of LAG3 driven by IL6 led to decreased function of peripheral CD8 + T cells and reduced tumor therapeutic resistance." (PMID 38115039, 2023). "Then, we examined the exhaustion markers, programmed cell death protein 1 (PD-1), lymphocyte activation gene 3 (LAG-3), and T cell immunoglobin and mucin-domain containing-3 (TIM-3) on the surface of TCR-JUN and TCR T cells following tumor antigen stimulation." (PMID 37215108, 2023). "Our results showed that SEMA4D knockdown delays tumor growth and resulted in a significant decrease in PD1, LAG3, and TIM3 expression in TME, and a trend of decreased TIGIT expression." (PMID 37287907, 2023). "Increasing evidence reveals a tumor cell-intrinsic expression of immune receptors, including the CD28 family member CTLA-4 as well as other checkpoint receptors like LAG3, TIGIT, and PD-1 in various malignancies." (PMID 37259155, 2023). "High LAG-3 and FGL1 expression has been shown to support tumor growth via accelerating T cell exhaustion and blocking T cell proliferation." (PMID 37427115, 2023). "It is homologous to CD4 but has a greater affinity for MHC class II molecules; additionally, LAG-3 can bind to LSECtin and FGL1, which are expressed by some tumor cells." (PMID 36960057, 2023). "In tumor tissues and lymph nodes, the expression of T-bet, PD-1, TIM-3, and LAG-3 genes in the Anti LIF group showed a significant increase." (PMID 37393300, 2023). "First, we found that the tumor infiltrating TCR-JUN T cells are less exhausted than the TCR T cells, with significantly less expression of double positive PD-1 and LAG-3 inhibitory receptors on the surface of TCR-JUN T cells." (PMID 37215108, 2023). "Similar to GC, higher infiltration levels of exhausted TIGIT+CD8+ T cells are observed in CRC tumor tissues with low levels of killer cytokines, including IFN-γ, IL-2, and TNF-α, but higher inhibitory receptors expression, such as PD-1, LAG-3, and TIM-3." (PMID 37180158, 2023). "Relatlimab blocks the lymphocyte-activation gene 3 (LAG-3) to also prevent immune suppression and allow for an anti-tumor response." (PMID 37764213, 2023). "In preclinical models, the combination of anti-LAG-3 and anti-PD1 reduced tumor size and provided a survival benefit, and a recent phase I study using tebotelimab found a partial response in a patient with MPM." (PMID 38136333, 2023).
tumor (continued). "Lymphocyte-activation gene 3 (LAG3) and PD-1 are distinct inhibitory immune checkpoints often co-expressed on tumor-infiltrating lymphocytes and contributing to tumor-mediated T-cell exhaustion." (PMID 37880788, 2023). "Another study, complementary to ours, analyzed the expressions of IDO, VISTA, LAG3, and TIM3 in tumor-infiltrating lymphocytes in PDAC patients from the PANCALYZE study cohort." (PMID 36768480, 2023). "When expressed on the surface of tumor cells in the TME, Gal-3 interacts with LAG-3 on CD8+ T lymphocytes inhibit cytotoxicity of CD8+ T lymphocytes." (PMID 37345111, 2023). "In the present work, we identified two tumour-infiltrating lymphocyte subsets with high expression of CD103 and LAG3, including a CD8+ T-cell and a B-cell subset." (PMID 37488535, 2023). "We also observed that with DC/tumor fusion vaccines stimulation, EGFRvIII Nb-CAR-T cells had more acquired expression of LAG-3, TIM-3 compared to other groups." (PMID 37771772, 2023). "In late-stage MC38 tumours, CD8+ TILs displayed a profoundly exhausted phenotype characterised by simultaneous expression of multiple inhibitory receptors (PD-1, TIM-3, LAG-3 and CD39) and low expression of CD127." (PMID 37153625, 2023). "The expression level of gene sets related to cytotoxic T cell activation (perforin, granzyme A, and granzyme B), costimulation (CD80 and CD86), and immune checkpoints (LAG3, CTLA4, PD-L1, and PD-1) was found to be increased in the tumor tissue." (PMID 37606040, 2023). "LAG-3 is expressed by activated T cells, NK cells, B cells, and DC and binds to the MHC class II (MHC-II) or to the galectin-3 (Gal-3) expressed by tumor cells." (PMID 37046702, 2023). "Expressed on the cell membrane of tumor-infiltrating lymphocytes (TIL), on activated CD4+ and CD8+ T cells, and on regulatory T cells (Treg), LAG-3 binds to MHC-II on APC." (PMID 37484526, 2023). "Tumor-derived androgen also alters IFN-γ and increases the expression of the exhaustion markers PD-1 and Lag3, effects reversed upon simultaneous inhibition of KAT2A and Tyr kinases." (PMID 37738978, 2023). "Given the high proportion of effector T cells within TIL we next used flow cytometry to assess the pattern of coexpression of checkpoint proteins PD-1, TIGIT, Tim-3, LAG-3, and CTLA-4 on T cells within the tumor microenvironment and peripheral blood." (PMID 36689623, 2023). "We observed that as compared to PBMC (peripheral blood mononuclear cells), CD8+ T cells at the tumor site exhibited dramatic increase in the expression of PD1, CD38, and Tim3, while Lag3 expression was comparable." (PMID 37566017, 2023). "The major immune checkpoints include PDCD-1, CD274 (also known as PD-L1), CTLA-4, HAVCR2 (also called TIM-3), LAG-3 and TIGIT which are responsible for tumor immune escape." (PMID 37810780, 2023). "The blockade of one of PD-1, LAG-3, and CTLA-4 showed compensatory upregulation of other immune checkpoint molecules, enhancing their ability to suppress local T cells in a tumor model study." (PMID 38026944, 2023). "LAG-3 is mostly upregulated on exhausted T cells, especially in refractory EBV (+) GC tumours after standard treatment." (PMID 37735150, 2023). "Both LAG-3 and CTLA-4 can inhibit TCR signaling pathway, thus resulting in immune tolerance of tumor cells." (PMID 37484526, 2023). "LAG3 expression is significantly higher on CD4+ and CD8+ tumor-infiltrating lymphocytes (TILs) than in other immune constituents among HCC patients." (PMID 36845131, 2023). "Fianlimab blocks the interaction between LAG-3 and MHC-II to activate T cells and enhance tumor cell damage mediated by cytotoxic T cells." (PMID 37670328, 2023). "LAG-3 is expressed on the surface of CD4 + and CD8 + T lymphocytes and inhibits the tumor immunological microenvironment by negatively affecting T cell proliferation and inducing T cell exhaustion." (PMID 37004702, 2023).